TRPM7 (transient receptor potential cation channel subfamily M member 7)
Diseases named in the same sentence as TRPM7 in open-access papers (continued):
Sharing a sentence is not in itself a finding about the gene and the disease.
lung carcinoma (continued). "(A) Kaplan-Meier analysis of TRPM7 gene expression in GSE37745 lung cancer dataset show patients with low TRPM7 expression had better overall survival than those with high TRPM7 expression." (PMID 30477473, 2018). "Coincidently, Waixenicin A treatment downregulated TRPM7 and oncogenic markers; Waixenicin A also attenuated the ability of lung cancer cells to form tumorspheres, in vitro." (PMID 30477473, 2018). "(B) Kaplan-Meier analysis of TRPM7 gene expression in GSE30219 lung cancer dataset show patients with low TRPM7 expression had longer relapse-free survival than those with high TRPM7 expression." (PMID 30477473, 2018). "Correspondingly, TRPM7 was aberrantly expressed in human lung cancer tissue samples and various cell lines and was found to be an independent indicator of poor prognosis in lung cancer." (PMID 38255793, 2024). "Moreover, increasing TRPM7 mRNA has been observed in tumor spheres derived from human lung cancer cells, accompanied by enhanced expression of the cancer stem cell markers SOX2, CD133, and KLF4." (PMID 35887116, 2022). "Similarly, upregulated TRPM7 enhances the lung cancer stem cell-like phenotype and promotes lung cancer metastasis via the Hsp90α/uPA/MMP2 signaling pathway." (PMID 35887116, 2022). "TRPM7/O-GlcNAc axis represents a potential novel target for lung cancer therapy that may overcome metastasis." (PMID 32684624, 2020). "Hence, waixenicin A was suggested as an anticancer therapy, by inhibiting lung cancer stem cells through TRPM7 inhibition." (PMID 30995736, 2019). "We speculate that the extracellular Hsp90 initiates EMT in lung cancer cells by modulating TRPM7 expression and activity." (PMID 30477473, 2018). "In this study, we demonstrated that the preferential overexpression of TRPM7 in lung cancer tissues and cell lines is not only statistically significant but also clinically relevant, as it bears poor prognostic implications in patients with lung cancer." (PMID 30477473, 2018). "To understand the role of TRPM7 in lung cancer, we analyzed the differential expression profile of TRPM7 in paired lung adenocarcinoma or squamous cell lung carcinoma and adjacent normal alveoli tissue samples from our lung cancer cohort, using immunohistochemical (IHC) staining." (PMID 30477473, 2018). "Furthermore, we showed for the first time that TRPM7 regulates the CSCs activities of lung cancer cells by modulating the Hsp90α/uPA/MMP2 signaling pathway." (PMID 30477473, 2018). "In addition, Silenced TRPM7 expression in lung cancer cells, markedly reduced their migration (~ 4.6-fold, p < 0.01) and invasion (~ 6.1-fold, p < 0.01) potential." (PMID 30477473, 2018). "We hypothesised that TRPM7 and Orai1 may be involved in the regulation of lung cancer metastasis." (PMID 32684624, 2020). "Furthermore, TRPM7-specific survival analysis of our lung cancer cohort showed that patients with high expression of TRPM7 exhibited worse cumulative survival than those with low TRPM7 expression (p < 0.001), with a 46.0 and 59.1% difference in survival at third and fifth year, respectively." (PMID 30477473, 2018). "The altered expression of these genes, as demonstrated in this study, may be reflective of the functional significance of TRPM7 in lung cancer cells, which to a large extent includes the maintenance of the lung cancer stem cell-like phenotypes and the suppression of lung metastasis." (PMID 30477473, 2018). "In human lung cancer cells, ligand-activation of EGF receptor has been shown to induce cell migration with up-regulation of TRPM7 channels." (PMID 25770184, 2015). "Lung cancer patients exhibit abnormal TRPM7 expression, which activates the Hsp90α/uPA/MMP2 signaling pathway and induces pluripotent transcription factors, thereby enhancing the metastatic phenotype of lung cancer." (PMID 39633507, 2024). "When TRPM7 was treated with the inhibitor Waixenicin A, lung cancer cells failed to form tumor spheres in vitro." (PMID 36142596, 2022).
lung carcinoma (continued). "Similarly, while TRPM7 protein expression was weak in the SV40-immortalized human bronchial epithelial 16-HBE cell line, TRPM7 was moderately expressed in SPCA-1 and NCI-H520, and strongly expressed in the SK-MES-1, A549 and 95D human lung cancer cell lines." (PMID 30477473, 2018). "In essence, we showed that targeting TRPM7 inhibits oncogenic activity, disrupts EMT in favor of the benign epithelial phenotype, inhibit cancer metastasis, attenuate cancer stemness, and increase sensitivity to chemotherapy and potentially results in better prognosis for lung cancer patients." (PMID 30477473, 2018).
hepatocellular carcinoma (14 papers, 2016 to 2025). A malignant tumor that arises from hepatocytes. "Cellular magnesium homeostasis is primarily maintained by TRPM7, whose overexpression and/or activation has been implicated in the growth and proliferation of hepatocellular carcinoma." (PMID 41562087, 2025). "Recently, it has been shown that RhoA interacts with TRPM7 through its kinase activity in hepatocellular carcinoma cells." (PMID 40274768, 2025). "Inhibition of the TRPM7/myocardin-related transcription factors A and B (MRTFs) axis is another promising strategy to curb hepatocellular carcinoma (HCC) growth." (PMID 36844925, 2022). "TRPC1 and TRPM7 were reported to be expressed in H4-IIE rat liver hepatoma cell lines, while TRPM2 channels were recently linked to APAP-induced oxidative stress and Ca2+ overload in mouse hepatocytes." (PMID 26903865, 2016). "In conclusion, this is the first study to systematically and comparatively analyze the contributions of redox-sensitive TRP channels such as TRPV1, TRPC1, TRPM2, and TRPM7 to human hepatoma cell death induced by APAP overdose." (PMID 26903865, 2016). "Interestingly, it has been shown that bradykinin increased TRPM7 expression in vascular smooth muscle cells and in hepatocellular carcinoma cells leading to enhanced cell migration." (PMID 35883700, 2022). "TRPM7 is found to interrupt the cell cycle distribution and cell apoptosis in breast and bladder cancer, and deregulates senescence in hepatocellular carcinoma." (PMID 33381038, 2020). "Also, a functional coupling between TRPM7 and RhoA activation dependent on the TRPM7 kinase activity on hepatocellular carcinoma has been shown." (PMID 33240883, 2020). "Among members of transient receptor potential (TRP) channels activated in response to oxidative stress, we here identify that redox-sensitive TRPV1, TRPC1, TRPM2, and TRPM7 channels underlie Ca2+ entry and downstream cellular damages induced by APAP in human hepatoma (HepG2) cells." (PMID 26903865, 2016). "Other studies showed expression of the TRPM7 channel in rat HSC-T6 hepatic stellate, RLC-18 and WIF-B hepatoma cells and of the TRPC1 channel in rat H4-IIE hepatoma cells." (PMID 26903865, 2016). "A previous study revealed that bradykinin could upregulate the levels of TRPM7 and MMP2 to promote the invasion and migration of hepatocellular carcinoma cells." (PMID 34938313, 2021).
colon carcinoma (13 papers, 2015 to 2024). "On the contrary, TRPM7 is downregulated in doxorubicin-resistant colon cancer cell line LoVo-R, therefore its silencing confers further resistance against doxorubicin, suggesting that the reduced expression of TRPM7 is linked to doxorubicin resistance in these cells." (PMID 32575381, 2020). "Furthermore, magnesium deficiency with physiological Ca2+ concentrations (i.e., increased Ca2+/Mg2+ ratio) was associated with increased TRPM7 expression, oxidative stress, induced calpain activity, increased cell migration and a more aggressive, metastatic phenotype of colon cancer cells." (PMID 38255793, 2024). "Colon cancer LoVo cells show high levels of TRPM7 and low amounts of MagT1, while the opposite is true in their doxorubicin-resistant counterpart." (PMID 36984673, 2023). "In previous studies, TRPM7 expression has been found in various cancers, such as glioblastoma, breast, ovarian, nasopharynx, and colon cancers." (PMID 36363540, 2022). "TRPM7 is also implicated as a player in colon-related chemoresistance, as colon carcinoma LoVo cells that remain sensitive to doxorubicin treatment exhibit higher TRPM7 expression compared to their drug-resistant counterparts." (PMID 28810912, 2017). "We demonstrate that the different amounts of TRPM7 and MagT1 account for the different proliferation rate of sensitive and resistant colon carcinoma cells." (PMID 28094304, 2017). "Taken together, our results indicate that TRPM7 appears to represent the major Mg2+-transporting mechanism in colon cancer HT-29 cells." (PMID 28810912, 2017). "To determine the involvement of TRPM7 in colon cancer cell proliferation, we next performed RNA interference (RNAi)." (PMID 28810912, 2017). "We find that TRPM7 drives colon cancer cell proliferation in human HT-29 and expresses in normal primary mouse colon epithelia." (PMID 28810912, 2017). "We also investigate the role of TRPM7 in modulating the sensitivity of LoVo cells to DXR and demonstrate that in this model of colon carcinoma cells drug resistance is associated with alteration of Mg homeostasis through modulation of TRPM7." (PMID 26563869, 2015). "TRPM7 expression has been demonstrated in a colon cancer LoVo cell line." (PMID 38255793, 2024). "The time-course experiment using a bolus injection of waixA allowed us to design experiments that could determine whether this TRPM7 inhibitor would prove protective in an early-stage colon cancer mouse model." (PMID 28810912, 2017). "Little is known about the biophysical and pharmacological properties of TRPM7 and TRPM6 in cell lines of mammalian colon cancer or primary colon epithelial cells." (PMID 28810912, 2017). "TRPM7 expression was higher in human colon tumor samples compared with that in non-neoplastic tissue, and adenocarcinomas showed a higher TRPM7 expression than did adenomas." (PMID 38255793, 2024). "In colon cancer, TRPM7 expression correlated with T stage; however, it was not statistically significant (p = 0.072)." (PMID 36363540, 2022). "Besides, colon cancer cells that are resistant to doxorubicin expressed lower amounts of TRPM6 and TRPM7." (PMID 31010205, 2019). "Silencing TRPM7 in different cell types, among which colon carcinoma cells, thymocytes and human endothelial cells, does not influence intracellular Mg content, while knocking down MagT1 in mammalian cell lines lowered the levels of intracellular Mg33." (PMID 30385806, 2018). "We conclude that chemically-induced early stage colon cancer proceeds independent of systemic Mg2+ status and propose waixA as a pharmacological tool in the study of TRPM7 in vitro and in vivo." (PMID 28810912, 2017). "Early stage colon cancer proceeds independent of systemic Mg2+ status and TRPM7, and waixenicin A is a useful pharmacological tool to study of TRPM7 in vitro and in vivo." (PMID 28810912, 2017). "In colon cancer, there were no variables that showed a significant correlation with TRPM7." (PMID 36363540, 2022).
colon carcinoma (continued). "No variables have a significant correlation to TRPM7 expression in colon cancer." (PMID 36363540, 2022).
nasopharyngeal carcinoma (13 papers, 2013 to 2025). A carcinoma arising from the nasopharyngeal epithelium. "For example, the increased expression of TRPM7 is associated with poor prognosis and metastasis in nasopharyngeal carcinoma." (PMID 36186485, 2022). "Knocking out the TRPM7 gene can increase the sensitivity of nasopharyngeal carcinoma patients to radiotherapy." (PMID 39759147, 2024). "A higher expression of TRPM7 proteins was found in a human nasopharyngeal carcinoma cell line exhibiting metastatic ability compared to cells without metastatic potential." (PMID 38255793, 2024). "TRPM7 is involved in the metastasis of nasopharyngeal carcinoma by enhancing the invasion and migration of nasopharyngeal carcinoma cells." (PMID 39759147, 2024). "Studies on tissue samples derived from patients with nasopharyngeal carcinoma showed that TRPM7 overexpression correlated with tumor metastasis and predicted poor prognosis (worse survival)." (PMID 38255793, 2024). "Studies suggest that nasopharyngeal carcinoma patients with TRPM7 overexpression have significantly shorter survival times compared to patients with low TRPM7 expression." (PMID 39759147, 2024). "Compared to high TRPM7 expression, nasopharyngeal carcinoma patients with low TRPM7 expression have higher survival rates." (PMID 39759147, 2024). "In nasopharyngeal carcinoma cells, bradykinin-induced stimulation and over-expression of TRPM7 increased migration, whereas inhibition (with La3+ or 2-APB) and RNAi silencing of TRPM7 inhibit migration." (PMID 32825277, 2020). "Similarly, TRPM7 promotes migration in nasopharyngeal carcinoma (NPC) cells and correlates with unfavorable clinical outcomes." (PMID 41155636, 2025). "The TRPM7 channel and TRPM7-mediated Ca2+ influx may be crucial for the migration of nasopharyngeal carcinoma cells." (PMID 39759147, 2024). "Moreover, the low expression of TRPM7 correlated with the better survival of patients with nasopharyngeal carcinoma." (PMID 38255793, 2024). "The contribution of TRPM7 function to cell migration of human nasopharyngeal carcinoma cells involves Ca2+-induced Ca2+ release, where TRPM7 activity promotes Ryanodine Receptor activation and, consequently, increases intracellular Ca2+ levels and cell migration." (PMID 31275168, 2019). "In addition, the migratory potential of nasopharyngeal carcinoma cells is decreased by extracellular Ca2+ chelators, TRPM7 inhibitors or TRPM7 knockdown." (PMID 27347718, 2016). "Moreover, TRPM7 regulates the migration of human nasopharyngeal carcinoma cells, suggesting its implication in metastasis; thus, TRPM7 inhibitors could be beneficial in cancer treatment." (PMID 23529027, 2013). "A pro-migratory role of TRPM7 was demonstrated in human nasopharyngeal carcinoma, in which overexpression of TRPM7 protein or increase in its Ca2+ channel activity significantly promoted the migration capability, whereas the interference with TRPM7 expression or activation decreased it." (PMID 23594099, 2013). "TRPM7 overexpression was found in 102 out of 206 nasopharyngeal carcinoma (NPC) tissues." (PMID 32887395, 2020). "Overexpression of TRPM7 can significantly enhance the migratory ability of non-metastatic nasopharyngeal carcinoma cells." (PMID 39759147, 2024). "It has been shown that TRPM7 knockdown in vitro decreases the migration and invasion of cancer cells and that TRPM7’s higher expression results in an increase in both migration and invasion in non-metastatic nasopharyngeal cancer cells." (PMID 36837670, 2023). "These clinical data are supported by in vitro assays showing that TRPM7 knockdown decreases the migration and invasion of metastatic nasopharyngeal cancer cells, and that TRPM7 overexpression results in increases in both processes in non-metastatic nasopharyngeal cancer cells." (PMID 31275168, 2019).
Parkinson disease (13 papers, 2014 to 2025). A progressive degenerative disorder of the central nervous system characterized by loss of dopamine producing neurons in the substantia nigra and the presence of Lewy bodies in the substantia nigra and locus coeruleus. "Looking at TRPM7, it has been proposed as a candidate susceptibility gene for familial Parkinson’s disease." (PMID 36613667, 2022). "Moreover, the missense variant c.C4446T in the TRPM7 gene was detected in a subgroup of patients suffering from Guamanian amyotrophic lateral sclerosis and the parkinsonism–dementia complex (ALS-G/PD-G)." (PMID 39125993, 2024). "Consistently, they also observed increased expression of apoptotic proteins and decreased TRPM7 levels in the samples obtained from the SNpc region of human Parkinson’s disease patients." (PMID 37842082, 2023). "On the contrary, in an experimental model of Parkinson’s disease induced by 6-hydroxy-dopamine, the total amounts of TRPM7 are increased, and the silencing TRPM7 is neuroprotective in pheochromocytoma PC12 cells." (PMID 36613667, 2022). "A TRPM7 mutation with a defective ion channel property has been identified in human patients with Guamanian amyotrophic lateral sclerosis and Parkinson’s disease, indicating a link between TRPM7 and neurodegenerative diseases." (PMID 34569930, 2021). "TRPM7 was reported to be involved in both excitotoxicity-related and neurodegenerative diseases such as epilepsy, Alzheimer’s disease (AD) and Parkinson disease (PD)." (PMID 32643506, 2020). "TRPM7 channels are selective to Ca2+ and Mg2+, and the discrepancy in TRPM7 channel function and expression leads to various neuronal diseases such as AD, Parkinson’s disease (PD) and ALS." (PMID 30090657, 2018). "Sun found the discrepancy in TRPM7 channel function and expression leads to Parkinson’s disease." (PMID 29422030, 2018). "We also reported rare heterozygous variants in neurodegenerative disease related genes, including TRPM7, MAPT, and APP that could be associated with parkinsonism phenotypes; however, none have been previously reported as pathogenic." (PMID 39867380, 2025).